CHKB-CPT1B (CHKB-CPT1B readthrough (NMD candidate))
Synonyms: CHKL-CPT1B; CPT1-M; CPT1B; CPTI-M
Gene: Protein-coding gene on chromosome 22 (50,568,869 to 50,582,965, reverse strand). Ensembl gene ENSG00000254413.
Genetic constraint (gnomAD): Missense variants: 73 observed, 74.62 expected, observed/expected ratio (o/e) 0.98, 90% interval 0.81 to 1.19. Synonymous variants: 28 observed, 28.66 expected, observed/expected ratio (o/e) 0.98, 90% interval 0.72 to 1.34.